APOA1 (apolipoprotein A1)
Diseases named in the same sentence as APOA1 in open-access papers (continued):
Sharing a sentence is not in itself a finding about the gene and the disease.
COVID-19 (continued). "Reduced HDL-C and ApoA1 compromises anti-inflammatory and antioxidant defense mechanisms, potentially worsening endothelial injury, oxidative stress, and thrombotic complications in COVID-19." (PMID 40565828, 2025). "In our study cohort, individuals infected with the omicron variant of COVID-19 exhibited markedly reduced serum levels of ApoA1 compared to those who were not infected." (PMID 40809523, 2025). "However, ApoA1 levels were significantly higher in comparison to t0 (p = 0 · 0063) in line with the finding of reduced ApoA1 serum levels for COVID-19 patients versus healthy controls." (PMID 36590898, 2023). "Remarkably, in the present study, APOA2 levels were also reduced in critical patients compared to mild ones, which is in agreement with the findings of a systematic review reporting that adequate levels of APOA1 were related to a protection against mortality in patients hospitalized for COVID-19." (PMID 37371071, 2023). "In contrast, ApoA1 levels were significantly lower in COVID-19 patients (p<0 · 0001)." (PMID 36590898, 2023). "Specifically, the patient group in which the apoA1 values were available may, on average, have had more severe cases, and if so, the results could be explained by the fact that patients with severe COVID-19, were treated with steroids, among other drugs." (PMID 37372137, 2023). "Serum ApoA1 is reduced with the progress of illness in COVID-19 patients." (PMID 35915785, 2022). "Apolipoproteins APOA1, APOA2, APOL1, and APOM, which have been previously reported to be associated with macrophage and decreased in COVID-19 patients, were all downregulated in the CSF from the eight COVID-19 patients." (PMID 34956212, 2021). "ApoA-1 and HDL levels were shown to be negatively correlated with CRP and IL-6 levels in patients with COVID-19, suggesting that the increased inflammatory response related to reduced HDL levels is one of the pathogenic mechanisms of COVID-19." (PMID 34335279, 2021). "In addition, ROC analysis verified the predictive value of HDL-C and apoA-1 levels for in-hospital death among COVID-19 patients." (PMID 33344516, 2020). "Moreover, it is important to note that the research did not explore the underlying mechanisms connecting ApoA1 with the severity and prognosis of omicron COVID-19, leaving a gap in understanding the biological processes involved." (PMID 40809523, 2025). "As SARS-CoV-2 is constantly mutating to generate new variants, it is possible that the results presented here on the role of HDL and apoA1 may not hold for the newer variants of COVID-19." (PMID 37372137, 2023). "Moreover, dysregulation of APP and APOA1 could both contribute to the possible adverse effects of COVID-19 on the nervous system." (PMID 33244380, 2020). "The following proteins have sparked interest in COVID-19 patients: XPNPEP2, HCII, ORP150, CREB3L3, APOA1, and CUBN." (PMID 38510452, 2024). "APOA1 and APOA isoforms, which are also involved in the immune response and dyslipidemia, have been frequently observed in COVID-19 patients with acute inflammatory conditions." (PMID 38396092, 2024). "The apolipoproteins APOA1, APOA2 and APOA4 showed a 30% to 90% decline in COVID-19 and/or ICU-ARDS observation frequency compared to Normals (NHP)." (PMID 37031181, 2023). "When levels of host proteins were compared between COVID-19 and TB patients, five (ApoA1, CRP, ferritin, SAA1/A2, and S100A12) showed promising discriminatory potential as all but ApoA1 were significantly higher in COVID-19 patients’ sera." (PMID 36590898, 2023). "The current study investigated the relationship of HDL and apoA1 with three different outcomes related to COVID-19, including SARS-CoV-2 infection, the severity of COVID-19, and the development of AKI as a result of COVID-19 in a single study." (PMID 37372137, 2023).
COVID-19 (continued). "Regarding the lipoprotein panel, for the main parameters the COVID-19 group is characterized by a significant increment of total TG and a decrement of total Chol, HDL-Chol, LDL-Chol, as well as of ApoA1 and ApoA2." (PMID 37943960, 2023). "Overall, our results were consistent with those of previous studies, suggesting that higher HDL and apoA1 levels protect against SARS-CoV-2 infection as well as severe outcomes of COVID-19." (PMID 37372137, 2023). "The study included fifty COVID-19 patients admitted to the intensive care unit (ICU) and found that apolipoprotein A1 and apolipoprotein B were significantly decreased in severe COVID-19 patients compared to non-severe patients." (PMID 38802549, 2024). "Apolipoprotein A1 (APOA-I) and Apolipoprotein M (APOM) are significant in severe COVID-19 cases." (PMID 36677438, 2023). "Our findings suggest that individuals with higher levels of high-density lipoprotein and apolipoprotein A1 were less likely to be infected with SARS-CoV-2 and were less likely to develop severe COVID-19 requiring hospitalization or invasive medical interventions." (PMID 37372137, 2023). "The observed differences in the protective effect of HDL in the N3C HDL population and the subpopulation with apoA1 measurements may thus reflect a more nuanced impact that the various subfractions of HDL are having on AKI and COVID-19." (PMID 37372137, 2023). "Furthermore, two additional markers ApoA1 and S100A12, also showed diagnostic potential for COVID-19 confirming the earlier reported downregulation of ApoA1 and the upregulation of S100A12 in COVID-19 patients in France and China." (PMID 36590898, 2023). "For the first time, to the best of our knowledge, we observed that this decrease in ApoA1 was lower in obese vs. non-obese, both before and during COVID-19." (PMID 35327501, 2022). "In particular, the COVID-19 group is characterized by a general increment of triglycerides (TG), and a decrement of phospholipids (Ph), total cholesterol (Chol), HDL- and LDL-cholesterol, as well as of apolipoprotein A1 and A2 (ApoA1 and ApoA2)." (PMID 35446921, 2022). "Using an NMR metabolomics approach, COVID-19 patients were characterized by alterations in several lipoproteins (decreased total and HDL apolipoprotein A1, low HDL triglycerides, and increased LDL and VLDL triglycerides) using quantitative measurements of lipoprotein subfractions." (PMID 35406806, 2022). "Genetic and epigenetic mosaicisms of non-polymorphic Alus as well as polymorphic Alus located in other genes, particularly the apolipoprotein cluster (APOA1, APOC3, APOA4) and HLA loci, could also influence the host response and disease outcomes of COVID-19." (PMID 33390179, 2021). "In addition, ROC analysis illustrated that decreased apoA-1 and HDL-C levels were strong predictors of COVID-19 severity." (PMID 33344516, 2020). "The underlying mechanisms of the pathogenesis and infection of S-COVID-19 could be better described by suggesting APP, EGF, C3, APOE, and APOA1 as the novel chief organizers of the network foundation." (PMID 33244380, 2020). "Also, other HDL-raising drugs that could be considered for the treatment of COVID-19 include CETP-inhibitors, fibrates and small molecules that increase APOA-1 synthesis." (PMID 40842550, 2025). "The COVID-19 convalescents had significantly elevated immunoglobulins, Orosomucoid 2 (ORM2), peroxiredoxin-2 (PRDX2), hemoglobin subunits (HBD, HBB and HBA1), as well as proteins involved in cholesterol transport such as cholesteryl ester transfer protein (CETP) and apolipoprotein A1 (APOA1)." (PMID 38396092, 2024). "Serum levels of apoA-1 and apoB did not correlate with COVID-19 severity." (PMID 35676519, 2022). "Thus, low apoA-1 and HDL-C levels may be promising predictors for severe disease and in-hospital mortality in patients suffering from COVID-19." (PMID 33344516, 2020).
COVID-19 (continued). "The interactions between ApoA1 and SAA proteins were also confirmed by XL-MS in pooled COVID-19 plasma without depletion of abundant proteins (173 cross-links across 117 proteins)." (PMID 37343697, 2023). "Both HDL and apoA1 values were higher in the subjects who tested negative for COVID-19 (54 mg/dL vs. 51 mg/dL with p < 0.001 for the HDL group and 144 mg/dL vs. 139 mg/dL with p = 0.002 for the apoA1 group)." (PMID 37372137, 2023). "For ApoA1, ferritin, IP-10, and SAA1/A2, no significantly different levels were observed at hospital admission – between COVID-19 patients with moderate disease, severe disease or fatal outcome." (PMID 36590898, 2023). "This did not allow us to identify COVID-19 patients with the highest probability to benefit from CER-001 and whether specific sub-phenotypes (according to the degree of inflammation, vasculopathy, or other parameters to be determined) may better respond to ApoA-1 supplementation." (PMID 36225555, 2022).
ovarian carcinoma (57 papers, 2007 to 2025). A malignant neoplasm originating from the surface ovarian epithelium. "OVA1 is an FDA-approved blood test that measures the levels of five proteins (CA125, transferrin, transthyretin, apolipoprotein A1, and beta-2 microglobulin) to detect ovarian cancer risk in women." (PMID 36232415, 2022). "In this context, higher serum ApoA1 levels are associated with better prognosis and longer overall survival among patients suffering from ovarian cancer." (PMID 30745873, 2018). "The aim of this study was to evaluate multiplexed bead-based immunoassay of multiple ovarian cancer-associated biomarkers such as transthyretin and apolipoprotein A1, together with CA125, to improve the identification and evaluation of prognosis of ovarian cancer." (PMID 22970327, 2012). "Higher APOA1 mRNA levels in pre-chemotherapy effusions from advanced-stage ovarian cancer patients are observed to be an independent prognostic marker with longer overall survival." (PMID 40836974, 2024). "In ovarian cancer patients, low serum APOA1 levels were detected, suggesting early-stage ovarian cancer, with a sensitivity of 54% and a specificity of 98%." (PMID 38067270, 2023). "In vitro, human ApoA1 reduced cell viability of ovarian cancer cells and prevented their invasion into the extracellular matrix." (PMID 36050733, 2022). "In the field of gynecological oncology, proteomic studies have shown that APOA1 is highly expressed in platinum-based chemotherapy-resistant ovarian cancer when compared to the levels in paracancerous tissue." (PMID 35421932, 2022). "Some studies have reported that APOA1 can be used as a predictive marker for platinum-based chemotherapy resistance in ovarian cancer." (PMID 35421932, 2022). "In gynecological tumors, it has been reported that APOA1 levels are significantly downregulated in patients with epithelial ovarian cancer serum, and APOA1 is a potential tumor marker for epithelial ovarian cancer." (PMID 35421932, 2022). "In studies of advanced ovarian cancer, high APOA1 mRNA levels in body fluids were found to be an independent diagnostic factor for clinically longer overall survival (OS)." (PMID 35421932, 2022). "It has further been substantiated that the APOA1 protein concentration in blood is reduced in different types of cancer, like ovarian cancer and hepatocellular cancer." (PMID 34440141, 2021). "Treatment with APOA1 and the mimetic peptide was reported to decrease the viability and prevented cell invasion of ovarian cancer." (PMID 34211824, 2021). "APOA1 was identified as a candidate drug resistance biomarker for ovarian cancer via 2D-gel proteomics." (PMID 34737677, 2021). "The combination of CA125, transferrin, TTR and ApoA1, using a proteomic analysis, yielded a sensitivity of 89% at a specificity of 92% for the early detection of ovarian cancer." (PMID 33800113, 2021). "APOA1 has been identified as a potential biomarker of ovarian cancer, colorectal cancer, and pancreatic cancer." (PMID 34440141, 2021). "APOA1 mRNA expression has been used as a biomarker for diagnosis and longer survival rates of ovarian cancer." (PMID 35052372, 2021). "APOA1 and AGP are acute-phase reactants, and their serum levels have been assessed in epithelial ovarian cancer to assess their potential as diagnostic or prognostic predictive biomarkers." (PMID 32224886, 2020). "The multivariate index assay (MIA) for ovarian cancer is composed of CA 125, beta 2-microglobulin, apolipoprotein A1 (ApoA1), transferrin, and prealbumin." (PMID 29843758, 2018). "Relatively to ovarian malignancies, overexpression of human ApoA1 also decreased tumor volume, prevented metastatic growth and increased survival in a transgenic mouse model of ovarian cancer." (PMID 30745873, 2018). "We aimed to disclose the effects of ApoA1 and a mimetic peptide on the malignant phenotype of ovarian cancer cells, particularly regarding cell viability, invasiveness and platinum sensitization." (PMID 30745873, 2018).
ovarian carcinoma (continued). "Survival studies in mouse models with ovarian cancer revealed higher levels of APOA1 to play a role in increased survival." (PMID 28469129, 2017). "The second test approved by the FDA, OVA1TM Ovarian Triage Test, combines a panel of five biomarkers for ovarian cancer (CA-125, transthyretin, apolipoprotein A1, ß2-microglobulin, and transferrin) identified through serum proteomics using SELDI-TOF-MS." (PMID 28837575, 2017). "APOA1 is also part of the OVA1 test for ovarian cancer which utilizes APOA1, transthyretin, transferin, CA-125 and β2-microglobulin as the panel biomarkers." (PMID 26463353, 2016). "When CA125 was combined with the biomarkers (transthyretin and apolipoprotein A1), the overall sensitivity and specificity for discriminating between ovarian cancer and healthy individuals were significantly improved in the ROC curve." (PMID 22970327, 2012). "Recently, a truncated variant of transthyretin together with apolipoprotein A1 and a connective tissue activating protein III were described as an efficient panel of new biomarkers for detecting early stage epithelial ovarian cancer in women." (PMID 22970327, 2012). "Recently, apolipoprotein A1 was shown to enhance the sensitivity of CA125 for detecting early stage epithelial ovarian cancer and suggested a promising therapeutic agent for the treatment of ovarian cancer." (PMID 22970327, 2012). "While transthyretin and apolipoprotein A1 have been used several times as potential biomarkers of ovarian cancer, the three-biomarker panel was newly evaluated using our Korean population." (PMID 22970327, 2012). "Apolipoprotein A1 has been identified as a potential biomarker of ovarian cancer, colorectal cancer, chronic obstructive pulmonary disease and pancreatic cancer." (PMID 22970327, 2012). "The serum levels of CA125 was significantly higher in ovarian cancer patients than that in healthy individuals and benign patients, while the levels of transthyretin and apolipoprotein A1 were lower in ovarian cancer patients." (PMID 22970327, 2012). "More strikingly, the sensitivity in distinguishing normal versus mucinous early stage ovarian cancer, utilizing apoA-1, TF and TTR (CA125 excluded), was 95% (specificity 86%; AUC 95%)." (PMID 19662218, 2007). "A significant decrease in plasma APOA1 level was observed in endometrium and ovarian cancers." (PMID 40778280, 2025). "Additionally, multiplexed magnetic nanoparticle-antibody conjugates combining MUC16, B2M, and APOA1 achieved high sensitivity (94%) and specificity (98%) in distinguishing early-stage ovarian cancer patients from healthy individuals." (PMID 40836974, 2024). "However, the clinical development of TTR, B2M and APOA1 as biomarkers for ovarian cancer is still ongoing." (PMID 40836974, 2024). "The loss of APOA1, APOA2, and APOA4 was reported in ovarian cancer patients." (PMID 38067270, 2023). "APOA1 was found to have a suppressive effect on ovarian cancer." (PMID 38067270, 2023). "Furthermore, treatment with the ApoA1 mimetic increased sensitivity of ovarian cancer cells to the chemotherapy cisplatin." (PMID 36050733, 2022). "Therefore, the in ovo findings substantiate the in vitro results demonstrating the ability of the ApoA1 mimetic to induce cisplatin sensitization in ovarian cancer cells." (PMID 30745873, 2018). "For example, ApoA1 exerts an essential role in ovarian physiology and ovarian steroidogenesis and indeed the levels of this apolipoprotein are remarkably decreased in both serum and ovarian tissue of patients suffering from ovarian cancer." (PMID 30745873, 2018). "In order to investigate whether human plasmatic ApoA1 affects ovarian cancer cells viability, we analyzed the effect of ApoA1, added to the extracellular medium, on the viability of SKOV3 cells." (PMID 30745873, 2018).